ALKBH5 (alkB homolog 5, RNA demethylase)
Diseases named in the same sentence as ALKBH5 in open-access papers (continued):
Sharing a sentence is not in itself a finding about the gene and the disease.
keloid (3 papers, 2022 to 2025). An irregularly shaped, elevated mark on the skin caused by deposits of excessive amounts of collagen during wound healing. "Then they constructed a keloid diagnostic Lasso model based on 5 genes and divided keloid samples into high-risk and low-risk groups, showing that m6A regulators ALKBH5, FTO, and HNRNPA2B1 were upregulated in the high-risk group, while YTHDF2 was downregulated." (PMID 40860194, 2025). "In this study, we demonstrated that ALKBH5 inhibits YTHDF2‐m6A‐mediated degradation of RCN1 mRNA to promote keloid formation by activating IRE1α‐XBP1‐mediated ER stress." (PMID 40214031, 2025). "Among all m6A regulators, the levels of METTL3 and WTAP were significantly higher in keloid samples, while the levels of ALKBH5, FTO, and METTL14 exhibited little differences." (PMID 40860194, 2025). "Through detecting the protein expression of ALKBH5 and RCN1 in keloid fibroblasts, we confirmed that the transfection of pcDNA‐ALKBH5 and shRNA were successful." (PMID 40214031, 2025). "Additionally, the efficiency of ALKBH5 overexpression was examined, which showed that it significantly promoted the expression of ALKBH5 in keloid fibroblasts." (PMID 40214031, 2025). "Our data revealed that RCN1 was upregulated by ALKBH5 to promote keloid formation by activating IRE1α‐XBP1‐mediated ER stress, RCN1 may be a potential biomarker for treatment of keloid." (PMID 40214031, 2025). "MTT assay revealed that overexpression of ALKBH5 significantly promoted the proliferation of keloid fibroblasts, which could be restored by silencing of RCN1." (PMID 40214031, 2025). "We observed an increase in the protein expression of ALKBH5 in keloid fibroblasts, indicating that ALKBH5 may play a regulatory role in keloid formation." (PMID 40214031, 2025). "Moreover, there are reported that ALKBH5 promote the keloid fibroblasts proliferation, migration and invasion." (PMID 40214031, 2025). "qPCR and Western blotting analysis showed that overexpression of ALKBH5 notably promoted the mRNA and protein levels of α‐SMA and COL1A1 in keloid fibroblasts." (PMID 40214031, 2025). "The results of Western blotting indicated that the protein expression of ALKBH5, RCN1, IRE1α, and XBP1 were increased in skin tissues of keloid mice, and knockdown of RCN1 reversed the changes." (PMID 40214031, 2025). "Taken together, these results confirmed that ALKBH5 played a vital role in the regulation of RCN1 in the proliferation, invasion, and apoptosis of keloid fibroblasts." (PMID 40214031, 2025). "However, the function and mechanism of ALKBH5 in keloid remain unclear." (PMID 40214031, 2025). "Furthermore, overexpression of ALKBH5 inhibited cell apoptosis and promoted cell invasion, but this change was abolished with the intervention of knockdown of RCN1 in keloid fibroblasts." (PMID 40214031, 2025). "But there is no significant change in METTL14, FTO, and ALKBH5 between these two groups (data are not shown), which indicates that the keloid is under a hypermethylated condition." (PMID 36263010, 2022).
leukopenia (3 papers, 2020 to 2022). "In addition, the level of peripheral blood ALKBH5 in SLE patients was associated with clinical symptoms of SLE such as rash, ulceration, and leukopenia." (PMID 32685056, 2020). "ALKBH5 also had correlations with clinical manifestations of patients with SLE, including rash, oral ulceration, and leukopenia." (PMID 36465909, 2022).
Lung Injury (3 papers, 2024 to 2025). "In septic lung injury mice, Alkbh5 is highly expressed, promoting the demethylation of m6A on Ccl1 mRNA, thereby reducing the stability of Ccl1 mRNA and decreasing Ccl1 expression." (PMID 40254698, 2025). "In the present study, we uncovered the function of ALKBH5 as a protector against I/R-induced liver injury." (PMID 39519091, 2024). "Functional assays demonstrated that Alkbh5 deficiency attenuated LPS-induced acute lung injury (ALI), characterized by reduced serum markers of lung injury, diminished immune cell infiltration, fibrosis, and apoptosis, whereas Alkbh5 overexpression exacerbated pathological damage." (PMID 41562066, 2025).
lung squamous cell carcinoma (3 papers, 2021 to 2023). "Compared with the low-risk lung squamous cell carcinoma patients, the expressions of ALKBH5, METL3, HNRNPC, and KIAA1429 were significantly reduced in patients with high-risk lung squamous cell carcinoma." (PMID 34956201, 2021). "In lung squamous cell carcinoma, reduced KIAA1429, ALKBH5, METTL3, and HNRNPC expressions were predictive of better responses to chemotherapy and immunotherapy." (PMID 36831575, 2023).
metastatic melanoma (3 papers, 2021 to 2024). A melanoma that has spread from its primary site to another anatomic site. "The expression of the LLGL1 gene was found to be upregulated by ALKBH5 in xenograft tumours, while ALKBH5 and MIEF2 were upregulated together in the T regulatory cells of metastatic melanoma." (PMID 39596561, 2024).
ocular melanoma (3 papers, 2019 to 2022). A melanoma that arises from the structures of the eye or ocular adnexa. "Genome-wide RNA-seq and GSEA of ocular melanoma cells further demonstrated these antitumor effects of higher m6A modification levels and identified major target gene clusters of ALKBH5." (PMID 31722709, 2019). "Notably, we found that knockdown of HINT2 only partially rescued the effect of knockdown of ALKBH5 on ocular melanoma cells, which indicates that there are other cofactors involved in tumorigenesis that are regulated by m6A modifications." (PMID 31722709, 2019). "Accordingly, decreased METTL3 and upregulated ALKBH5 were observed in ocular melanoma cells." (PMID 31722709, 2019). "Notably, the expression of the known m6A “writer” METTL3 was also decreased in ocular melanoma tissue compared to normal melanocyte tissue (p < 0.05), while the opposite trend was observed for m6A “eraser” ALKBH5 (p < 0.01)." (PMID 31722709, 2019). "m6A modification was decreased in ocular melanoma due to METTL3 downregulation and ALKBH5 upregulation, which promoted YTHDF1-mediated translation of histidine triad nucleotide-binding protein 2 (HINT-2), a tumor suppressor of ocular melanoma." (PMID 35164788, 2022). "Thus, the decreased m6A level in ocular melanoma cells is likely due to the downregulation of METTL3 and upregulation of ALKBH5." (PMID 31722709, 2019).
periodontitis (3 papers, 2021 to 2022). An acute or chronic inflammatory process that affects the tissues that surround and support the teeth. "For instance, monocyte abundance is positively correlated with ALKBH5 and negatively correlated with FMR1, indicating increased monocytes infiltrated in periodontitis which is closely affected by the expression of ALKBH5 and FMR1." (PMID 33724691, 2021). "ALKBH5 is also up‐regulated in subtype‐2 and periodontitis; these results may suggest ALKBH5, IL6‐STAT3, activated B cells and periodontitis have great correlations." (PMID 33724691, 2021). "In addition, Alkbh5 was related to the infiltration of monocytes in periodontitis, of which regulated m6A mediated the immune reaction of TNF-family-member receptors and cytokines, indicating the crucial roles of m6A in the diversity and complexity of the immune microenvironment of periodontitis." (PMID 36225914, 2022).
sarcoma (3 papers, 2022 to 2023). A usually aggressive malignant neoplasm of the soft tissue or bone. "m6A is removed by demethylases such as FTO and ALKBH5, whose expression levels were significantly correlated with those of KCNH2 in PRAD, sarcoma (SARC), PAAD, and TGCT." (PMID 36792990, 2023).
Stroke (3 papers, 2022 to 2024). Sudden impairment of blood flow to a part of the brain due to occlusion or rupture of an artery to the brain. "YTHDF1-regulated STAT5 translation mediates the protective role of ALKBH5 in stroke." (PMID 39519091, 2024). "FTO has been reported to promote angiogenesis and reduce myocardial fibrosis after myocardial ischemia, however, in the brain, it is predominantly expressed in neurons, whereas downregulation of FTO and ALKBH5 after stroke can induce secondary brain injury by destroying neurons." (PMID 35747214, 2022). "Our study showed that ALKBH5 protein decreased in 3d group but increased in 7d group, suggesting that it could be one of the potential targets for treatment of stroke, and increases in demethylase may improve cerebral infarction by changing the m6A modification." (PMID 35747214, 2022). "In a rat stroke model, the protein levels of demethylases FTO and ALKBH5 were changed, both FTO and ALKBH5 co-regulated m6A demethylation, which played a crucial role in cerebral ischemia/reperfusion (I/R) injury." (PMID 36246528, 2022). "Additionally, we further showed that ALKBH5 and YTHDF3 proteins were changed at different times after stroke." (PMID 35747214, 2022).
triple-negative breast carcinoma (3 papers, 2016 to 2025). An invasive breast carcinoma which is negative for expression of estrogen receptor (ER), progesterone receptor (PR), and human epidermal growth factor receptor 2 (HER2). "However, little is known about the role of m6A regulator AlkB homolog 5 (ALKBH5) in triple-negative breast cancer (TNBC)." (PMID 36551544, 2022).
cervical squamous cell carcinoma (2 papers, 2023 to 2024). A squamous cell carcinoma arising from the cervical epithelium. "In cervical squamous cell carcinoma (CESC), ALKBH5 and IGF2BP1 target silent mating type information regulation 2 homolog 3 (SIRT3), reducing its stability, subsequently inhibiting ACC1 deacetylation and lipid metabolism and ultimately repressing CESC." (PMID 37055798, 2023).
cutaneous melanoma (2 papers, 2021 to 2024). A primary melanoma arising from atypical melanocytes in the skin. "Recent studies have shown remarkable progress in linking m6A RNA demethylation with fat mass and obesity-associated protein (FTO) and ALKBH5, which is strongly associated with cutaneous melanoma development and reactions to cancer therapy." (PMID 34291082, 2021).
cytomegalovirus infection (2 papers, 2021 to 2022). A herpesvirus infection caused by Cytomegalovirus. "It was also observed that ALKBH5 overexpression strongly reduced the increased levels of MCU protein induced by HCMV infection but did not affect the total MCU mRNA." (PMID 35359726, 2022). "Our experiments saw consistent results in vascular endothelial cells, with a slight difference that we did not see an increase in the demethylases ALKBH5 and FTO after HCMV infection." (PMID 35359726, 2022). "Although our previous results showed that the expression of ALKBH5 and FTO did not change after HCMV infection, we still wondered whether ALKBH5 or FTO was involved in the HCMV-mediated m6A methylation of MCU mRNA." (PMID 35359726, 2022).
dental pulp inflammation (2 papers, 2018 to 2023). "The results showed that there were significant differences in the genes ALKBH5, METTL14, METTL3, METTL16, RBM15B and YTHDF1 between normal group and the pulpitis group." (PMID 37978362, 2023). "However, YTHDF1, YTHDF3, METTL16 and METTL3 gene expression were not statistically different between the pulpitis group and the control group, and RBM15B, ZCCHC4 and ALKBH5 were up-regulated." (PMID 37978362, 2023).
diabetic cardiomyopathy (2 papers, 2025 to 2026). Diabetic cardiomyopathy is a disorder of the heart muscle in people with diabetes. "The levels of the RNA methylase ALKBH5 and the ferroptosis marker GPX4 were significantly decreased in diabetic cardiomyopathy patients with myocardial tissue injury." (PMID 40548888, 2025).
diabetic retinopathy (2 papers, 2022 to 2026). "Lower expression A20 resulted in the enhanced M1 polarization of retinal microglia in diabetic retinopathy, which was caused by ALKBH5 mediated m6A modification." (PMID 35300330, 2022). "In terms of mechanism, lower expression of ALKBH5 led to higher m6A modification level and faster degradation rate of A20 mRNA, which at last resulted in decreasing A20 expression in retinal microglia of diabetic retinopathy." (PMID 35300330, 2022). "In conclusion, we demonstrate that ALKBH5 mediated m6A modification of A20 regulated microglia polarization, which provides new insight into both the pathogenesis and the clinical intervention for diabetic retinopathy." (PMID 35300330, 2022).
Hyperglycemia (2 papers, 2023 to 2025). An increased concentration of glucose in the blood. "Using AAV-mediated shRNA and the clinically applicable GalNAc-siRNA technology, the specific knockdown of hepatic Alkbh5 reversed hyperglycemia, hyperlipidemia, and the MAFLD phenotype in the db/db mouse model." (PMID 40312430, 2025).
laryngeal squamous cell carcinoma (2 papers, 2022 to 2023). A squamous cell carcinoma that arises from the larynx. "The m6A demethylase ALKBH5-mediated m6A modification of lncRNA KCNQ1 overlapping transcript 1 promotes the proliferation, invasion, and metastasis of laryngeal squamous cell carcinoma cells by upregulating HOXA9." (PMID 36982798, 2023).
liver cirrhosis (2 papers, 2021 to 2022). "Besides, in gene clusterB, ALKBH5 expression levels were lower than in gene clusterA and its expression inversely associated with the macrophage infiltration suggesting it as a protective factor of liver cirrhosis." (PMID 35308519, 2022).
mastitis (2 papers, 2024 to 2025). Inflammation of breast tissue during lactation or postpartum due to an obstructed duct or infection. "Therefore, studying the interaction between ALKBH5 and p65 in protecting the mammary epithelial barrier provides new insights into the pathogenesis of mastitis." (PMID 40214476, 2025).
Nephropathy (2 papers, 2023 to 2025). A nonspecific term referring to disease or damage of the kidneys. "However, studies focusing on ALKBH5 and m6A modifications in renal diseases are limited, especially for kidney IRI." (PMID 36859428, 2023). "We then detected the mRNA expression of m6A methyltransferases (METTL3, METTL14, and WTAP) and demethyltransferases (FTO and ALKBH5) and found that METTL3 and FTO mRNA expression was upregulated in Pb-induced nephropathy compared with controls." (PMID 40520008, 2025).
Non-alcoholic fatty liver disease (2 papers, 2021 to 2024). "In the mouse model of non-alcoholic fatty liver disease (NAFLD), inhibiting the activity of ALKBH5 significantly induced hepatocytes autophagy by reducing the stability of AXL mRNA." (PMID 39220683, 2024).
Parkinson disease (2 papers, 2021 to 2025). A progressive degenerative disorder of the central nervous system characterized by loss of dopamine producing neurons in the substantia nigra and the presence of Lewy bodies in the substantia nigra and locus coeruleus. "In Parkinson’s disease mouse models, both gene expression and protein levels of ALKBH5 and IGF2BP2 in the substantia nigra were upregulated, which in consistent with the trend of ALKBH5 upregulation observed in aging cochleae, suggesting that ALKBH5 may play a significant role in geriatric disease." (PMID 40198960, 2025).
Peri-Implantitis (2 papers, 2023 to 2025). An inflammatory process with loss of supporting bone in the tissues surrounding functioning DENTAL IMPLANTS. "To investigate the impact of ALKBH5 on osteogenic differentiation in peri-implantitis combined with type II diabetes, we employed siRNAs to downregulate ALKBH5 expression in hMSC cells." (PMID 37519314, 2023). "When translating the preclinical findings to clinical practice, targeting ALKBH5 and m6A demethylation emerges as a promising strategy to enhance osteoblast differentiation and alleviate inflammation in peri-implantitis patients." (PMID 37519314, 2023). "The elevated m6A level and impaired expression of osteogenic markers further support the crucial role of ALKBH5 in regulating the osteogenic differentiation process in peri-implantitis combined with type II diabetes." (PMID 37519314, 2023). "Furthermore, ALKBH5 expression was found to be significantly decreased in diabetic peri-implantitis, indicating a strong link between ALKBH5 and osteoblast development and inflammation." (PMID 37519314, 2023). "Importantly, ALKBH5 expression was significantly downregulated (log fold change = −11.56) in the peri-implantitis combined with type II diabetes group." (PMID 37519314, 2023). "RNA sequencing revealed that ALKBH5 expression was abnormally reduced in diabetic peri-implantitis." (PMID 37519314, 2023).
preeclampsia (2 papers, 2024 to 2025). Preeclampsia is a hypertensive disorder of pregnancy that is characterized by new-onset hypertension with proteinuria presenting after 20 weeks of gestation, and depending on mild or severe forms may initially present with severe headache, visual disturbances, and hyperreflexia. "At the mechanistic level, the expression of the RNA demethylase ALKBH5 is notably elevated in placental tissues affected by preeclampsia." (PMID 40356909, 2025). "Mouse experiments showed that inhibition of ALKBH5 alleviated preeclampsia-like symptoms through the Wnt/β-catenin pathway (Guo, Song & Yang, 2022)." (PMID 39434797, 2024). "However, others have reported a significant increase in the expression level of ALKBH5 in placentas from preeclampsia patients, as well as in cells subjected to hypoxia or reoxidation." (PMID 40356909, 2025).
rectal cancer (2 papers, 2021 to 2023). A primary or metastatic malignant neoplasm that affects the rectum. "Here, we found that ALKBH5 was highly expressed in radiosensitive rectal cancer tissues and expressed at low levels in radioresistant tissues." (PMID 37381158, 2023).
renal carcinoma (2 papers, 2020 to 2021). A carcinoma arising from the epithelium of the renal parenchyma or the renal pelvis. "By contrast, low levels of the m6A erasers FTO and ALKBH5 are linked with poor renal carcinoma prognosis." (PMID 33232910, 2021). "A recent study showed that ALKBH5 expression was suppressed in renal carcinoma compared to adjacent healthy tissues." (PMID 33364952, 2020).
testicular germ cell tumor (2 papers, 2020). A germ cell tumor arising from the testis. "Some studies have shown that METTL3, ALKBH5, YTHDC1, YTHDF1, YTHDF2, and HNRNPC are the main m6A-related genes in type II testicular germ cell tumors." (PMID 32258108, 2020).